IL10RB (interleukin 10 receptor subunit beta)
Diseases named in the same sentence as IL10RB in open-access papers (continued):
Sharing a sentence is not in itself a finding about the gene and the disease.
inflammatory bowel disease (11 papers, 2013 to 2025). A spectrum of small and large bowel inflammatory diseases of unknown etiology. "Data indicates IL10RB rs2834167 is also associated with Inflammatory Bowel Disease and systemic sclerosis." (PMID 35205336, 2022). "Loss of function mutations affecting any of the two genes encoding interleukin-10 receptor (IL10RA or IL10RB genes); or affecting the gene encoding the cytokine IL-10 (IL-10 gene), will cause early-onset inflammatory bowel disease." (PMID 32737687, 2020). "Accordingly, defects of IL10, IL10RA, or IL10RB genes cause very early-onset inflammatory bowel disease (IBD) including infantile-onset IBD (IOIBD)." (PMID 26822028, 2016). "The importance of IL-10 in intestinal immunity is also illustrated by the identification of mutations in IL-10, IL-10RA, and IL-10RB genes in children suffering from inflammatory bowel disease (IBD)." (PMID 30915067, 2019). "It has been shown that individuals with severe immune-mediated diseases, such as very early onset inflammatory bowel disease (VEOIBD) and autoimmune thyroid diseases, have polymorphisms in IL-10 and its receptors, IL-10RA and IL-10RB." (PMID 36992353, 2023). "There are, however, certain rare forms of IBD, particularly in pediatric patients, that can be classified as monogenic, which are caused by mutations in single genes like IL10RA, IL10RB, or XIAP genes, and often present as very early-onset inflammatory bowel disease (VEO-IBD)." (PMID 40611267, 2025).
glioma (6 papers, 2017 to 2024). A benign or malignant brain and spinal cord tumor that arises from glial cells (astrocytes, oligodendrocytes, ependymal cells). "Previous literature characterizes IL10 as immunosuppressive and finds only positive associations between serum IL10 or genetic expression of IL10RB and glioma." (PMID 28594935, 2017). "In addition to these, MAPKAPK2 is positively correlated with IL6, IL6R, IL10, IL10RB, TGFβ1, etc., in the present study, which may facilitate the glioma progression." (PMID 38322416, 2024). "Then, we selected the top 5 relevant immunomodulators, including an immunostimulator (CD276), two immunoinhibitors (IL10RB and TGFBR1), a chemokine (CXCL10) and an MHC (HLA-A), in the glioma dataset and drew scatterplots to show their details." (PMID 37006287, 2023). "In particular, its high correlation with IL-10RB and TGFRB suggested that PDCL3 may be involved in the immunosuppression of glioma." (PMID 37006287, 2023).
Obesity (5 papers, 2018 to 2026). Accumulation of substantial excess body fat. "The aim of the present study was to investigate the relationship between SNPs of the IL10 and IL10RB genes and the risk of obesity in young men." (PMID 35205336, 2022). "Some of the studies indicate polymorphisms in IL10 and IL10RB genes as associated with obesity." (PMID 35205336, 2022). "For DE RNAs of obesity-related ccRCC in SAT, 4 mRNAs (ENO2, YY1AP1, FAP, IL10RB) and 1 miRNA (hsa-miR-425) were eligible for the following risk score analyses." (PMID 34621242, 2021). "For DE RNAs of obesity in SAT, 4 mRNAs (ENO2, YY1AP1, FAP, IL10RB) and 1 miRNA (hsa-miR-425) were found." (PMID 34621242, 2021). "Similarly, apabetalone differentially reduced gene expression of the phagocytic macrophage receptor CD68, of the IL-10 receptor subunit IL10RB implicated in pro- and anti-inflammatory homeostasis, and of MTMR14 encoding a phosphoinositide phosphatase involved in metabolic dysregulation in obesity." (PMID 33172487, 2020).
Alzheimer disease (4 papers, 2022 to 2025). A progressive, neurodegenerative disease characterized by loss of function and death of nerve cells in several areas of the brain leading to loss of cognitive function such as memory and language. "In addition, a subunit of the IL-10 receptor (IL-10RB) was significantly associated with all-cause dementia and Alzheimer’s disease." (PMID 36085081, 2022). "Elevated expression of IL10RB has been observed in the brains of Alzheimer's disease (AD) patients and mouse models, suggesting a potential role in AD pathogenesis." (PMID 40936594, 2025).
Arthritis (4 papers, 2014 to 2023). Inflammation of a joint. "AR IL-10RB deficiency can also underlie perianal lesions, skin folliculitis, B-cell lymphoma, and arthritis, which were not seen in our patients." (PMID 36308662, 2023). "Interestingly, some of haplotypes, such as the IL10RB CGA haplotype, acted protectively toward arthritis occurrence, and at the same time, this haplotype was more frequent in the patients with thrombocytopenia and nephritis." (PMID 37511050, 2023). "Five of the 13 chemokines that decreased in the whole group decreased in the 7 children with arthritis as well, and three of those chemokines were the ones for which decreases remained significant after adjustment for multiple comparisons: CX3CL1, SCF and IL-10RB." (PMID 34112181, 2021).
Down syndrome (4 papers, 2020 to 2025). "Analyses of IL10RB rs2834167 genotype distribution in the Down syndrome patient group showed a significant reduction of homozygous A genotype compared to the expected HW equilibrium frequency." (PMID 33260695, 2020). "For example, four IFN receptor genes (IFNAR1, IFNAR2, IFNGR2, and IL10RB) and two IFN-stimulated genes (MX1 and MX2) are triplicated in Down syndrome, and individuals with Down syndrome exhibit hypersensitivity to type I IFN (IFN-I)." (PMID 38540156, 2024).
Hepatitis (4 papers, 2013 to 2023). Inflammation of the liver. "Collectively, these data strongly suggest that homozygosity for the W100G variant of IL10RB was the cause of EOIBD, and perhaps also of severe hepatitis, in the two affected siblings from this family." (PMID 36308662, 2023).
viral infection (4 papers, 2013 to 2021). "The IL10RB and IFNAR2 share an inverse relationship for viral infection, wherein macrophages have been reported to secrete higher IL10 in comparison to IFNAR246." (PMID 34315903, 2021).
hepatoma (3 papers, 2011 to 2020). "HBV replication in hepatoma cells expressing IL-10RB K47 or E47 in response to IFN- λ or IL-22 was determined to explore whether the single nucleotide polymorphism of an IL-10RB extracellular domain affects the cellular response to IL-22 and IFN-λ." (PMID 23519428, 2013). "The effect of IFN-λ or IL-22 on HBV replication and cell viability was assessed in hepatoma cells expressing IL-10RB K47 or E47." (PMID 23519428, 2013). "The transcript level of IL-10RB was examined in Epstein Barr virus-transformed B cells and hepatoma cells." (PMID 23519428, 2013). "This study focused on the association of IL-10RB K47E with the effects of IFN-λ and IL-22 in cultured hepatoma cells." (PMID 23519428, 2013). "IL-10RB K47E was associated with the transcript level of IL-10RB in transformed B cells but not with the responses in hepatoma cells to IFN-λ or IL-22." (PMID 23519428, 2013). "IL-10RB K47E was associated with chronic HBV infection but not with hepatoma in the Korean population." (PMID 23519428, 2013). "We do not know the reason for the lack of association of IL-10RB K47E with IL-10RB expression level in hepatoma cell lines, but the limited number of hepatoma cell lines we analyzed may be one factor." (PMID 23519428, 2013). "However, similar levels of IL-10RB expression were observed in hepatoma cell lines regardless of their genotype." (PMID 23519428, 2013).
influenza (3 papers, 2014 to 2023). An acute viral infection of the respiratory tract, occurring in isolated cases, in epidemics, or in pandemics; it is caused by serologically different strains of viruses (influenzaviruses) designated A, B, and C, has a 3-day incubation period, and usually lasts for 3 to 10 days. "Here we demonstrate in both mouse and human models that influenza significantly induces IL-22Ra1 but not IL-10Rb (data not shown)." (PMID 31416461, 2019).
atherosclerosis (2 papers, 2018 to 2025). A disease characterized by the build-up of fatty material and calcium deposition in the arterial wall resulting in partial or complete occlusion of the arterial lumen. "Reduced expression of IL10RB may enhance anti-inflammatory effects, leading to improved immune surveillance and a reduction in the inflammatory burden associated with atherosclerosis and endothelial dysfunction." (PMID 40429759, 2025). "It is crucial to investigate how IL10RB expression influences immune responses at the molecular and cellular level, particularly how it impacts inflammatory mediators that drive the pathogenesis of atherosclerosis and endothelial dysfunction." (PMID 40429759, 2025). "IL10RB is a key component of the Interleukin-10 (IL-10) receptor complex, a potent anti-inflammatory cytokine critical for regulating immune responses and modulating inflammation in atherosclerosis and endothelial dysfunction." (PMID 40429759, 2025).
autoimmune thyroid disease (2 papers, 2023 to 2025). Inflammatory disease of the thyroid gland due to autoimmune responses leading to lymphocytic infiltration of the gland. "Increased IL-10 expression has been reported in autoimmune thyroid diseases, suggesting that anti-inflammatory responses may occur simultaneously via IL10RB, DUSP1, DUSP2, and RGS1 in GD." (PMID 40710355, 2025).
benign thymic neoplasms (2 papers, 2024). "The primary IVW MR analysis revealed that higher levels of IL10RB were significantly associated with a reduced risk of benign thymic neoplasms (OR = 2.394; 95% CI: 1.203 to 4.766; p = 0.013)." (PMID 39769247, 2024). "By combining the causal estimates from the two MR steps, we calculated that approximately 5.95% of the protective effect of physical activity on benign thymic neoplasms is mediated via reductions in IL10RB levels." (PMID 39769247, 2024). "Approximately 5.95% of the protective effect on benign thymic neoplasms was mediated via reductions in IL10RB levels." (PMID 39769247, 2024). "Our mediation analysis identified IL10RB as a partial mediator in the relationship between physical activity and benign thymic neoplasms." (PMID 39769247, 2024). "Finally, we estimated the indirect effect of physical activity on benign thymic neoplasms mediated through IL10RB levels." (PMID 39769247, 2024).
colorectal cancer (2 papers, 2017 to 2020). A primary or metastatic malignant neoplasm that affects the colon or rectum. "IL-10RB is overexpressed in colorectal cancer and through binding of IL-22 contributes to colorectal carcinogenesis." (PMID 33075095, 2020).
glioblastoma (2 papers, 2015). The most malignant astrocytic tumor (WHO grade IV). "We identified a six gene cytokine-related signature (CCL2, CCR2, CXCL10, IL10RB, IL17B, and IL17R) capable of dividing glioblastoma patients into a low risk score group with favorable survival and a high risk score group with poor survival." (PMID 25978454, 2015).
Hypertension (2 papers, 2014 to 2022). The presence of chronic increased pressure in the systemic arterial system. "DNA variants in IL10rb, a subunit of IL10R, have been associated with ischemic stroke in individuals with hypertension, and IL10 deficiency has been associated with preeclampsia, a condition characterised by high blood pressure during pregnancy." (PMID 25259444, 2014).
leukemia (2 papers, 2021). A malignant (clonal) hematologic disorder, involving hematopoietic stem cells and characterized by the presence of primitive or atypical myeloid or lymphoid cells in the bone marrow and the blood. "We further show that TR1 cell-mediated control of TCL1 leukemia requires IL-10 receptor (IL-10R) signaling, as Il10rb-deficient CD4+ T cells showed impaired antileukemia activity." (PMID 33526861, 2021). "Either Il10rb+/+ (WT) or Il10rb−/− CD4+ T cells were injected into Rag2−/− mice followed by transplantation of TCL1 leukemia." (PMID 33526861, 2021). "We speculated that it might be due to the far lower expression of IL-10RB in T cells than that in AML cell lines or primary leukemia cells." (PMID 34392305, 2021). "Unlike the expression of IL-10R on leukemia cell lines or primary leukemia cells, the expression of IL-10A or IL-10RB on CD34+ UCB cells was much lower." (PMID 34392305, 2021).
liver cirrhosis (2 papers, 2013 to 2024). "Presently, the association of IL-10RB K47E with outcomes of HBV infection was assessed in 1,000 Koreans, including 751 patients with chronic HBV infection (including liver cirrhosis and HCC) and 249 patients who had spontaneously recovered from HBV infection." (PMID 23519428, 2013).
pancreatic tumor (2 papers, 2020 to 2024). "In pancreatic tumor tissue as well as in pancreatic tumor cell lines, IL10RB and IL20RA were co-expressed and enable IL26 signaling." (PMID 31948053, 2020).
ZIKV infection (2 papers, 2019). "To evaluate this hypothesis, we measured the levels of Ifnlr1, Il10rb, Ifnl2, and Ifnl3 mRNA by RT-qPCR in the vagina on days 1, 4, and 7 after ZIKV infection." (PMID 30655513, 2019). "ZIKV infection also increased expression of mRNAs for both IFNLR1 and IL10RB components of the IFNλ heterodimeric receptor complex and the SOCS1 and SOCS3 negative regulators of IFN signaling." (PMID 31289325, 2019).
acute disseminated encephalomyelitis (1 paper, 2024). Acute disseminated encephalomyelitis (ADEM) is a demyelinating disorder of the central nervous system. "Inflammatory factors potentially causally associated with acute disseminated encephalomyelitis are monocyte chemoattractant protein 2, interleukin-10 receptor subunit beta and matrix metalloproteinase-1." (PMID 40008261, 2024). "However, interleukin-10 receptor subunit beta levels (OR=0.562; 95% CI=0.277-0.961, p = 0.011) were potentially negatively associated with acute disseminated encephalomyelitis." (PMID 40008261, 2024).
Allergy (1 paper, 2024). An allergy is an immune response or reaction to substances that are usually not harmful. "IL-6 rs1800795G allele (in particular GG genotype) was increased in the allergy patient group as well as IL-10 rs1800896AA genotype and IL-10RB rs2834167G/* positive genotypes." (PMID 39202464, 2024). "At this moment, to our knowledge, this is the first observation of the relationship among variants of IL-10RB and allergic diseases." (PMID 39202464, 2024). "Formal statistical analyses show that IL-6 rs1800795GG, IL-10RB rs2834167G positive genotypes, IL-13 rs1800925CC, CD23 rs2228137TT Klotho rs564481TT, might be risk factors for allergy." (PMID 39202464, 2024).
Autoimmunity (1 paper, 2024). The occurrence of an immune reaction against the organism's own cells or tissues. "The other nodes of the network mainly contain genes/proteins related to autoinflammatory/autoimmunity, such as JAK1, STAT3, STAT5B, IL10RA, and IL10RB, with SOCS3 as a hub." (PMID 39359477, 2024).
benign ovarian tumors (1 paper, 2020). "Using LASSO regression, a multiplex model including 6 biomarkers (HE4, CA125, ITGAV, CXCL1, CEACAM1, IL-10RB) and age had the highest diagnostic accuracy for discrimination between benign ovarian tumors and EOC including borderline tumors." (PMID 33075095, 2020).
breast carcinoma (1 paper, 2024). "IL-10R2 (also known as IL-10RB), which serves as the IL-22 receptor, received the most weight in the regression model as an indicator of poor prognosis and has not been studied earlier in clinical breast cancer materials at all." (PMID 38594742, 2024).
chronic granulomatous disease (1 paper, 2023). Chronic granulomatous disease (CGD) is a rare primary immunodeficiency, mainly affecting phagocytes, which is characterized by an increased susceptibility to severe and recurrent bacterial and fungal infections, along with the development of granulomas. "IEI other than AID was subdivided into Inflammatory bowel disease 25 (IL10RB; n = 1), chronic granulomatous disease (CYBB; n = 1), tricho-hepato-enteric syndrome 1 (TTC37; n = 1) and CVID with hypogammaglobulinemia (MS4A1; n = 1)." (PMID 36777733, 2023). "Remarkably, in 3 of these 26 patients, an IEI different to AID was diagnosed based on genetic results (IL10RB defect, chronic granulomatous disease, and tricho-hepato-enteric syndrome)." (PMID 36777733, 2023).
cognitive decline (1 paper, 2022). "Assessment of the relationship of SNPs, which are associated with the risk of suicide, with cognitive decline in older adults showed potential significance for rs4918918 in the SORBS1 gene and rs10903034 in the IFNLR1/IL10RB gene." (PMID 36421848, 2022).
diabetes (1 paper, 2025). "Nine biomarkers were positively associated with depressive symptoms in the total sample (CCL11/eotaxin, CCL25, CDCP1, FGF-21, IL-8, IL-10RB, IL-18, MMP-10, TNFRSF9; all p < 0.05) without interaction by diabetes type." (PMID 39799156, 2025).
endometrial cancer (1 paper, 2024). Primary or metastatic malignant neoplasm involving the endometrium (mucous membrane that lines the endometrial cavity). "We subsequently explored the expression of the IL-10 receptors IL-10RA and IL-10RB in endometrial cancer cell lines." (PMID 38459564, 2024).
endometrioid carcinoma (1 paper, 2014). "Furthermore, the R198W substitution mutation in IL-10RB (from the COSMIC database), also destroys the interaction between IL-10 and IL-10RB, and this mutation is observed in endometrioid carcinoma." (PMID 25056661, 2014).
enterocolitis (1 paper, 2020). An inflammatory process affecting the small intestine and colon. "Also patients with deleterious mutations in IL10, IL10RA or IL10RB develop severe enterocolitis in the first few months of life." (PMID 33240582, 2020).
epilepsy (1 paper, 2013). A brain disorder characterized by episodes of abnormally increased neuronal discharge resulting in transient episodes of sensory or motor neurological dysfunction, or psychic dysfunction. "Increased expression of Il10rb (unpaired two-tailed t test, p = 9.3E-03) was inversely correlated with a hypomethylation phenotype in chronic rat epilepsy." (PMID 24005891, 2013). "Therefore, overexpression of IL10rb in rat epilepsy could be a compensatory mechanism to limit brain damage following seizures." (PMID 24005891, 2013).
fulminant viral hepatitis (1 paper, 2023). Fulminant viral hepatitis is a rapid and severe impairment of liver functions (acute liver failure) with hepatic encephalopathy developing less than 8 weeks after the onset of jaundice, secondary to viral hepatitis mainly due to HBV, but also to HAV. "Further studies are required to compare the clinical manifestations and cellular responses to IL-10, IL-22, IL-26, and IFN-λ1 of patients with IL-10RB deficiency, with or without fulminant viral hepatitis." (PMID 36308662, 2023).
Hashimoto thyroiditis (1 paper, 2023). An autoimmune disorder caused by the production of autoantibodies against thyroid tissue. "The IL10RA, IL10RB, and IL22RA polymorphisms/haplotypes could be associated with SLE susceptibility and various clinical manifestations, and the IL22RA CC haplotype could be associated with Hashimoto thyroiditis." (PMID 37511050, 2023).
HIV-1 infection (1 paper, 2010). The type species of lentivirus and the etiologic agent of acquired immunodeficiency syndrome (AIDS). "One SNP in IL10RB (rs2266590 in intron; 4 p = 0.05) and one in IL20 (rs2981572 in 5′UTR; p = 0.006) were associated with risk of HIV-1 infection." (PMID 20976276, 2010). "Here, we hypothesize that involvement of the IL-10 molecule in HIV-1 infection and pathogenesis could be modulated through complex interactions among IL10 and its related genes, especially those (IL19, IL20 and IL24) in the flanking genomic region and the IL-10 receptor genes (IL10RA and IL10RB)." (PMID 20976276, 2010).
lymphopenia (1 paper, 2025). Reduction in the number of lymphocytes. "At month three, LC patients had elevated IL10RB and MCP-1, whereas by month six, levels of several proteins (monocyte chemoattractant proteins MCP2/CCL8 and MCP4/CCL13, lymphopenia associated IL2RB, and TGF-signaling LAP/TGFb1) had fallen." (PMID 40572685, 2025).